NDUFA6 (NADH:ubiquinone oxidoreductase subunit A6)
Description:
Accessory subunit of the mitochondrial membrane respiratory chain NADH dehydrogenase (Complex I), that is believed to be not involved in catalysis. Required for proper complex I assembly. Complex I functions in the transfer of electrons from NADH to the respiratory chain. The immediate electron acceptor for the enzyme is believed to be ubiquinone.
Synonyms: CI-B14; LYRM6; NADHB14; B14; MC1DN33
Tractability: Small molecule: an approved drug acts on it; a structure with a bound ligand is known. Antibody: UniProt places it where antibodies can reach, with high confidence. PROTAC: ubiquitination databases record sites on it; its protein half-life has been measured.
Gene: Protein-coding gene on chromosome 22 (42,085,526 to 42,090,884, reverse strand). Ensembl gene ENSG00000184983.
Subcellular location: Mitochondrion inner membrane
Subcellular location (Human Protein Atlas): End piece; Nucleoplasm; Mid piece; Vesicles
Pathways (Reactome):
Metabolism: Complex I biogenesis; Respiratory electron transport
Gene Ontology:
Molecular function: NADH dehydrogenase (ubiquinone) activity
Biological process: mitochondrial respiratory chain complex I assembly; aerobic respiration; mitochondrial electron transport, NADH to ubiquinone; proton motive force-driven mitochondrial ATP synthesis; proton transmembrane transport
Cellular component: mitochondrial inner membrane; mitochondrial membrane; mitochondrion; respiratory chain complex I
Genetic constraint (gnomAD): Loss-of-function variants: 9 observed, 10.22 expected, observed/expected ratio (o/e) 0.88, 90% interval 0.53 to 1.52. The upper end of that interval is the gene's LOEUF score, 1.52, which puts it in group 6 of 6, group 1 being the genes least tolerant of losing a copy. Missense variants: 172 observed, 180.73 expected, observed/expected ratio (o/e) 0.95, 90% interval 0.84 to 1.08. Synonymous variants: 66 observed, 66.75 expected, observed/expected ratio (o/e) 0.99, 90% interval 0.81 to 1.21.
Gene-disease validity (ClinGen):
ClinGen rates the evidence that NDUFA6 causes each of these diseases.
mitochondrial disease (autosomal recessive): Moderate.
Homologues: Orthologues: chimpanzee NDUFA6 (100% identical), macaque NDUFA6 (97% identical), rabbit NDUFA6 (89% identical), dog NDUFA6 (88% identical), guinea pig NDUFA6 (88% identical), mouse Ndufa6 (88% identical), pig NDUFA6 (88% identical), rat Ndufa6 (88% identical), zebrafish ndufa6 (73% identical), tropical clawed frog ndufa6 (55% identical), Drosophila melanogaster ND-B14 (46% identical), Caenorhabditis elegans nuo-3 (32% identical).
Diseases named in the same sentence as NDUFA6 in open-access papers:
NDUFA6 is named in the same sentence as 29 diseases in open-access papers, as found by Europe PMC text mining. Sharing a sentence is not in itself a finding about the gene and the disease. The quoted sentences say what the papers report.
Alzheimer disease (3 papers, 2019 to 2022). A progressive, neurodegenerative disease characterized by loss of function and death of nerve cells in several areas of the brain leading to loss of cognitive function such as memory and language. "Notably, we identified that CO therapy decreased the expression of genes encoding ETC complex I genes: NDUFB4, NDUFS2, NDUFAB1, NDUFA6, NDUFB9, also enriched in Parkinson’s, Huntington’s and Alzheimer disease pathways." (PMID 31615996, 2019). "This “Alzheimer’s disease” pathway overlaps with other AV-1451-associated pathways that relate to mitochondrial respiration, electron transport, and oxidative phosphorylation (NDUFS4 & 8, NDUFA6 &7, UQCRQ, & COX17), as well as metabolism (NDUFS4 & 8, NDUFA6 &7, UQCRQ, COX17, & ETHE1)." (PMID 35774552, 2022). "Of the three AD pathologies probed by PET imaging, Tau deposition (by AV-1451) appears to reveal the most relevant pathways related to AD, as well as including “Alzheimer’s disease” itself as the most highly significant BioPlanet-identified pathway via NDUFS4 & 8, NDUFA6 & 7 and UQCRQ." (PMID 35774552, 2022).
Cognitive impairment (2 papers, 2020 to 2024). Abnormal cognition is characterized by deficits in thinking, reasoning, or remembering. "In participants with cognitive impairment, the expression levels of KEGG:M00146’s NDUFA2, NDUFA3, NDUFA4, NDUFA6, NDUFA7, NDUFA10, and NDUFA12 increased, but the expression levels of NDUFA5, NDUFA4L2, and NDUFAB1 marginally decreased." (PMID 38542318, 2024).
COVID-19 (2 papers, 2023 to 2025). A disease caused by infection with severe acute respiratory syndrome coronavirus 2. "Among these 16 protein-coding genes, the roles of BTN3A1, EIF5A, and NDUFA6 were previously identified in the pathogenesis of COVID-19, suggesting a potential link between their expression and the development of Long COVID." (PMID 41325417, 2025).
multiple myeloma (2 papers, 2022 to 2023). "Several researches have reported that NDUFA6 was correlated with prognosis of multiple myeloma and was involved in mitochondrial fitness to promote proliferation in glioblastoma cells." (PMID 37259038, 2023). "Additionally, relapsed/refractory myeloma patients expressed significantly higher expression of NDUFB8, NDUFA6, COX6C, and USMG5 than newly diagnosed patients." (PMID 36551283, 2022). "Our results indicate that NDUFB8, NDUFA6, COX6C, COX5B, and USMG5 might influence the immune microenvironment of multiple myeloma patients, as well as the response to treatment and prognosis of patients with this disease." (PMID 36551283, 2022).
Anxiety (1 paper, 2021). Intense feelings of nervousness, tension, or panic often arise in response to interpersonal stresses. "It was observed that the expressions of Gys1, Chka, Ncstn, and Ndufa6 were significantly down-regulated whereas Pgp, Klc1, and Kyat1 were up-regulated in the anxiety-susceptible group as compared to the control group." (PMID 33737865, 2021). "The results indicated that Atp6v1f, Arpc5, Adcyap1r1, Ndufb6, and Psmc6 were distinctly dysregulated in the hypothalamus of the depression-susceptible group, while Gys1, Pgp, Klc1, Chka, Ncstn, Ndufa6, and Kyat1 were distinctly dysregulated in the anxiety-susceptible group." (PMID 33737865, 2021).
breast carcinoma (1 paper, 2024). "Consistent with the present findings, breast cancer patients with high NDUFA6 levels had shorter OS." (PMID 39533394, 2024).
heart failure (1 paper, 2024). Inability of the heart to pump blood at an adequate rate to meet tissue metabolic requirements. "The NDUFA6 p.Ile94LysfsTer44 variant has been reported in a patient with recurrent exertional rhabdomyolysis, and the C1QBP p.Thr40AsnfsTer45 and PPA2 p.Glu172Lys variants have been reported in autosomal recessive mitochondrial cardiomyopathies with heart failure and sudden cardiac death." (PMID 39457051, 2024).
lactic acidosis (1 paper, 2021). Metabolic acidosis characterized by the accumulation of lactate in the body. "Ndufa6 is a subunit of complex I, and its inhibition may induce unintended side effects, as a previous study demonstrated that complex I inhibition results in glycolysis enhancement and lactic acidosis." (PMID 34793269, 2021).
melanoma (1 paper, 2024). A malignant, usually aggressive tumor composed of atypical, neoplastic melanocytes. "We previously performed unbiased proteomic analysis on the mitochondria of AP-4-139B treated melanoma cells and identified novel HSP70 client proteins including MRPS14 and NDUFA6." (PMID 38802657, 2024).
Obesity (1 paper, 2021). Accumulation of substantial excess body fat. "Our results suggested that Ndufa6 may be a therapeutic target for obesity." (PMID 34793269, 2021). "Therefore, on the basis of our study, the development and proper selection of Ndufa6 inhibitors may contribute to the treatment of obesity." (PMID 34793269, 2021). "Therefore, the Ndufa6–Scd1 pathway can be a key therapeutic target for the management of obesity." (PMID 34793269, 2021).
psoriasis (1 paper, 2021). An autoimmune condition characterized by red, well-delineated plaques with silvery scales that are usually on the extensor surfaces and scalp. "In blood heat syndrome, a common syndrome of psoriasis, we found that a large number of oxidative phosphorylation pathway-related genes, such as NDUFS8, NDUFA6, and UQCRC1, showed syndrome-specific expression abnormalities." (PMID 35126107, 2021).
schizophrenia (1 paper, 2023). A major psychotic disorder characterized by abnormalities in the perception or expression of reality. "Only one study reports that the missense schizophrenia risk variant rs1801311 (located in the 1st exon of NDUFA6 gene) can disrupt the binding of YY1, TAF1, and POLR2A." (PMID 36680208, 2023).
tumor (4 papers, 2019 to 2025). "High levels of NDUFA6 expression were found to predict increased tamoxifen treatment failure and tumor recurrence in high-risk ER-positive breast cancer patients at diagnosis." (PMID 31344832, 2019).
cancer (3 papers, 2019 to 2024). A tumor composed of atypical neoplastic, often pleomorphic cells that invade other tissues. "Finally, we found that the experimentally validated translated lncRNA ZFSA1 promoted cancer cell migration by elevating cellular ROS production via the expression downregulation of NADH dehydrogenase expression (NDUFA6, NDUFB4, and NDUFB11)." (PMID 31781169, 2019). "Recent research evidence has revealed that lncRNA ZFAS1 can encode a small peptide to down-regulate NADH dehydrogenase expression (NDUFA6, NDUFB11 and NDUFB4) to enhance ROS production, thus promoting cancer development." (PMID 34888249, 2021). "Down-regulate NADH dehydrogenase expression (NDUFA6, NDUFB4, and NDUFB11) to enhance ROS production and thus promote cancer cell migration." (PMID 34888249, 2021). "Therefore, we propose that upregulated ZFAS1 promotes cancer cell migration via elevating cellular ROS production by repressing the expression of NADH dehydrogenases, including NDUFA6, NDUFB4, and NDUFB11." (PMID 31781169, 2019).
neurodegenerative disease (1 paper, 2025). A disorder of the central nervous system characterized by gradual and progressive loss of neural tissue and neurologic function. "In the turquoise module, four hub lncRNAs (Gm5848, Zfp141, Rmrp, and Rb1) linked to hub mRNAs (Psmb3, Mad211, Sdhd, Ndufa6, Snrqd2, and Immp11) and are mainly related to NAFLD, multiple neurodegenerative diseases, oxidative phosphorylation, cell cycle, inflammation, and metabolic pathways." (PMID 40141450, 2025).
NDUFA6 also shares sentences with these, for which no sentence is quoted: infection (8 papers); viral infection (2); depression (1); endometriosis (1); glioblastoma (1); hematological disease (1); hepatocellular carcinoma (1); Huntington disease (1); Hypercholesterolemia (1); legionellosis (1); mental disorder (1); Parkinson’s (1); preeclampsia (1); psychiatric disorder (1).